RBL2 (RB transcriptional corepressor like 2)
Diseases named in the same sentence as RBL2 in open-access papers (continued):
Sharing a sentence is not in itself a finding about the gene and the disease.
ependymoma (1 paper, 2019). A WHO grade II, slow growing tumor of children and young adults, usually located intraventricularly. "LINC00899 knockdown in spinal ependymoma cells elevated levels of RBL2, p21, p27 and Bax; decreased levels of FoxO, Bcl-2, vimentin and annexin; reduced cell proliferation, migration and invasion; and enhanced apoptosis." (PMID 31739288, 2019).
esophageal squamous cell carcinoma (1 paper, 2014). Esophageal squamous cell carcinoma (ESCC) is a type of esophageal carcinoma (EC) that can affect any part of the esophagus, but is usually located in the upper or middle third. "SMAD4 is enriched in adherens junction and cell cycle pathways and has been found to have a potential predictive value for esophageal squamous cell carcinoma in patients receiving neoadjuvant chemoradiotherapy RBL2 and CDKN1B are enhanced in cell cycle pathways." (PMID 24604236, 2014).
hearing loss (1 paper, 2020). "An additional five genes have not previously been associated with human hearing loss but are known to cause hearing loss or cochlear development when mutated in mice: SYNJ2, RPGRIP1L, BAIAP2L2, TUB, and RBL2." (PMID 32986727, 2020).
melanoma (1 paper, 2022). A malignant, usually aggressive tumor composed of atypical, neoplastic melanocytes. "In other cancers like melanoma, the frequency of pocket protein paralogue alterations is comparable (melanoma RB1 = 5.6%, RBL1 = 5.9%, RBL2 = 3%)." (PMID 35368709, 2022).
microcephaly (1 paper, 2025). A congenital or acquired developmental disorder in which the circumference of the head is smaller than normal for the person's age and sex. "In concert with the microcephaly seen in RBL2 patients, these data reveal a conserved function of the RBL2 and Rbf proteins in controlling head and brain morphology during development." (PMID 39692517, 2025). "Given that microcephaly is a clinical feature of RBL2 patients, we next examined whether brain size was also reduced in Drosophila Rbf mutants." (PMID 39692517, 2025).
neuroendocrine tumors (1 paper, 2012). "We also found that RBL2, a key regulator of entry into cell division was significantly down-regulated in metastatic neuroendocrine tumors, suggesting growth-suppressive properties of RBL2 was decreased and tumor cells proloferate." (PMID 22485171, 2012).
pancreatic ductal adenocarcinoma (1 paper, 2018). An infiltrating adenocarcinoma that arises from the epithelial cells of the pancreas. "It has been determined that miR-17-5p promotes proliferation in pancreatic ductal adenocarcinoma cells by disrupting the RBL2/E2F4-associated gene repressing complexes." (PMID 30279327, 2018).
prostate carcinoma (1 paper, 2023). A carcinoma that arises from epithelial cells of the prostate gland. "Given that RB-related proteins, RBL1 and RBL2, can functionally compensate for loss of RB in some settings, we investigated whether a similar RBL1/RBL2/E2F/ACSL4 axis exists in human prostate cancer." (PMID 36928314, 2023). "We found that, similar to RB, depletion of RBL1 or RBL2 led to upregulation of ACSL4 and E2F-targeted genes and sensitized prostate cancer cells to ferroptosis induction." (PMID 36928314, 2023). "However, homozygous loss of RBL1 or RBL2 was rarely observed in metastatic castration-resistant prostate cancer samples from various data sets, and no positive association was found between ACSL4 expression and inactivation of RBL1 or RBL2." (PMID 36928314, 2023).
pulmonary disorder (1 paper, 2022). "Based on pathway enrichment analysis, genes altered in BPD blood cells were mainly enriched in cell cycle regulation and arrest (e.g., PPP2CA, RBL2, CENPU, CCNY, CDK6) and pulmonary disorder and developmental disorders (e.g., AGER, ITGA6, CA4, BACH2, IGFBP2, BMPR2, SKI, DAB2)." (PMID 35484630, 2022).
sarcopenia (1 paper, 2024). Progressive decline in muscle mass due to aging which results in decreased functional capacity of muscles. "Consistently across the three outcomes, RXRA, MDM1, RBL2, KCNJ2, and ADHFE1 were identified as risk factors, while NMB, TECPR2, MGAT3, ECHDC2, and GINM1 were identified as protective factors, all with potential as biomarkers for sarcopenia progression." (PMID 39409102, 2024).
teratocarcinoma (1 paper, 2013). A germ cell tumor characterized by the presence of an embryonal carcinoma component and a teratoma component. "They reported that human stem cells and teratocarcinoma cells show a selective reduction in the expression of E2F1, E2F2, E2F3 and p105 (encoded by NFKB1) and enhanced expression of E2F4, E2F5, E2F6 and p130 (encoded by RBL2) compared with human normal somatic IMR90 cells." (PMID 24355041, 2013).
teratoma (1 paper, 2018). A non-seminomatous germ cell tumor characterized by the presence of various tissues which correspond to the different germinal layers (endoderm, mesoderm, and ectoderm).
viral infections (1 paper, 2024). "However, there is limited information on the role of RBL2 in viral infections." (PMID 39337523, 2024).
tumor (77 papers, 2001 to 2025). "Among various Rbl2 mutations K1083R showed strongly positive association with tumor grads, whereas it had a mildly positive association to cooccur with S1080I and T1099P." (PMID 35385527, 2022). "It has been demonstrated that 3p107 (RBl1) and 3p130 (RBl2) deletions which are observed in most human SCLCs are particularly associated with tumor progression." (PMID 35620343, 2022). "P130, known as retinoblastoma-like protein 2 (RBL2), is a protein encoded by the RBL2 gene in humans and serves as a tumor suppressor signal." (PMID 31379957, 2019). "The results suggest that large subpopulations of tumor cells are in a senescent cell state characterized by expression of HP1γ, RBL2, and senescence associated cytokines and a cytokine receptor." (PMID 25093008, 2014). "The aim of this study was to investigate pRb2 expression in endemic BL cases from Uganda and to search for tumour-associated, somatic RBL2 mutations that could be involved in deregulated cell cycle control." (PMID 19691827, 2009). "BRMS1L, CPEB3, KIF3B, NEDD4L, PTPRJ, and RBL2 were significantly downregulated in tumor samples compared to controls." (PMID 40943553, 2025). "They additionally showed the correlation of miR-106a with HGSOC tumor growth and differentiation both in vivo and in vitro, confirming p130 (RBL2), a retinoblastoma (Rb) tumor suppressor family member, as a specific target of miR-106a." (PMID 37627777, 2023). "This analysis has therefore identified a mechanism by which the tumour suppressor RBL2 is repressed in TNBC and proposes that CBX2 promotes TNBC cell growth via inhibition of DREAM complex activity." (PMID 35884550, 2022). "RBL2 has been shown to suppress tumour growth in vivo, and downregulation of RBL2 has been reported in a number of cancers." (PMID 35884550, 2022). "The PCR array result showed, ectopic expression of TTPAL activated the expression of PI3K/AKT signaling-related genes while downregulated tumor suppressors, such as RBL2, PTEN, and CDKN1B (p27)." (PMID 34642500, 2021). "Subsequent models have included the inactivation of the Pten, Crebbp, or Rbl2 (also known as p130) tumor suppressors in the context of the RP model." (PMID 33296145, 2021). "This permitted the isolation of solitary quiescent (Ki67−/RBL2+/cleaved PARP−) BC cells within tumor masses." (PMID 32575420, 2020). "PRMT5 regulates this pathway through direct methylation of histones H3R8 and H4R3 in the promoter region of RB1, RBL1 and RBL2 tumor suppressor genes." (PMID 30613353, 2018). "The net outcome of these modifications is transcriptional repression of all three tumor suppressor genes; however, only RBL2 appears to be suppressed at the protein level." (PMID 30613353, 2018). "A similar function in HCC has also been illustrated for both of SMAD3 and RBL2 in the previous studies 43, 44, suggesting the significant function of SMAD3 and RBL2 as a tumor suppressor in HCC." (PMID 28639733, 2017). "Statistical analysis revealed that Rbl2/p130 expression negatively correlates to its promoter methylation (r = -0.412) in tumor tissues." (PMID 26271034, 2015). "High-risk alpha E7 represses the retinoblastoma family of tumor suppressors: RB1 (retinoblastoma), RBL1 (p107), and RBL2 (p130); E7 targets the degradation of RB1, which is tied to the cancer phenotype." (PMID 26470018, 2015). "Our IHC results for RB1 and RBL2 support the previous conclusion that large subpopulations of tumor cells are in a resting state." (PMID 25093008, 2014).
tumor (continued). "ATM and RBL2 are already known as negative regulators of cell cycle which support their role as tumor suppressor genes." (PMID 22485171, 2012). "The marker genes Myc, Glul and Oat presented pre-tumor-specific differential expression which was reverted in the tumor state, whereas Ccnd1, Gpc3, Mvk, Pparg, Rbl2, Robo1 were only upregulated in tumors." (PMID 21464922, 2011). "RBL2 is a putative tumour suppressor gene that constitutes part of the DREAM complex." (PMID 35884550, 2022). "A central question in the field is whether the additional genes in this family, RBL1 and RBL2, are important tumor suppressor genes." (PMID 35368709, 2022). "Interestingly, SFK or AKT inhibitors triggered apoptosis in MM cells by mechanisms dependent, respectively, on the expression of p27 and another key tumor suppressor co-regulated with p27, the RB family member RBL2/p130." (PMID 32664483, 2020). "Hyper-methylation in the region -10 to + 80 around TSS of Rbl2/p130 in tumor sample was observed." (PMID 26271034, 2015). "Similarly, Rbl2/p130 expression varies with age and disease stages (P = 0.022), which suggest its involvement in tumor progression." (PMID 26271034, 2015). "Finally, Ccnd1, Gpc3, Mvk, Pparg, Rbl2, and Robo1 exhibited a tumor-specific response, where adverse expression changes were observed for Pparg, which appeared down regulated in transgenic cells (fold change <0.4) and significantly up regulated in tumors." (PMID 21464922, 2011). "Thus, the discovery of paracrine functions for the tumour suppressor RBL2 paves the way for future investigations linking the regulation of early development and tumorigenesis, which has clear translational utility for devising more efficient cancer therapeutics in the future." (PMID 38678032, 2024). "Thus, RBL2 could control mechanisms in early development, which may be related to its function as a tumor suppressor." (PMID 37725511, 2023). "While further investigation is required, these data do suggest that CBX2 may inhibit the expression of the tumour suppressor RBL2 in multiple cancer types and, therefore, may repress RBL2-DREAM complex activity across multiple malignancies to promote cell growth." (PMID 35884550, 2022). "In addition, mutations in CREBBP, EP300, TP73, RBL1, RBL2 and NOTCH family genes are largely mutually exclusive, suggesting that they may play similar tumor-promoting roles in the onset of SCLC." (PMID 34168983, 2021). "Also, since the loss of RBL2/p130 expression and the hyperactivation of AKT signaling are common traits of many tumor entities, these findings may be potentially extended to other tumor types." (PMID 30652113, 2018).
tumor (continued). "Finally, gene expression studies revealed that NFs + Sali could upregulate expression of Rbl1 and Rbl2 tumor suppressor genes as well as caspase 3 that can lead to caspase-dependent apoptosis, and simultaneously decreased Wnt signaling pathway." (PMID 29925966, 2018). "To uncover the effect of RBL2 on WNT ligands in PDAC CSCs, we studied the paracrine effects on CSC self-renewal by tumour sphere assays." (PMID 38678032, 2024). "Our data are consistent with those of previous reports that the tumor suppressor properties of the RB1 gene are significantly stronger than those of RBL1 and RBL2 and that among RB family members only RB1 inactivation is commonly found in human cancer." (PMID 36928314, 2023). "We conclude that RBL1 and RBL2 do have important tumor suppressor activity in some contexts, but RB1 remains the dominant tumor suppressor in the family." (PMID 35368709, 2022). "Evidence for RB1 mediated tumor suppression is more readily detected across a wider spectrum of tissues and biological contexts while evidence for RBL1 and RBL2 tumor suppressor activity is more restricted." (PMID 35368709, 2022). "Conversely, loss of the endogenous CDK4/6 inhibitors (CDKN2A, CDKN2B, CDKN2C, and CDKN2D) or RB-family (RB1, RBL2, and RBL1) are also observed in specific tumor settings, in total the RB-pathway is subject to genetic perturbation in greater than 30% of tumors." (PMID 32242058, 2020). "In SCLC, overexpression of the miR-17~92 cluster including seven miRNAs promotes the tumor development through repressing tumor suppressor PTEN and RB transcriptional corepressor like 2 (RBL2)." (PMID 32316322, 2020). "This basic model was subsequently followed by variant versions when additional genetic modifications found or suspected in human SCLC tumors were introduced: inactivation of Rbl2, another member or the Rb family, resulted in accelerated SCLC tumor development." (PMID 33375066, 2020). "Recent findings in cancer research point to a role of this seed sequence in reinforcing the proliferative cellular program in a wide range of cancers, by repressing tumor suppressor genes such as PTEN, RBL2, LATS2, or CDKN1A." (PMID 30713549, 2018). "The mRNA levels of RBL2 (P=0.2687), SASH1 (P=0.0859), S100A8 (P=0.2198) and S100A9 (P=0.0731) were not significantly different between ER+-cancer tissues and ER+-tumor-adjacent tissues." (PMID 29416786, 2018). "Analysis of cell cycle pathway in KEGG of each differential list of genes showed that in normal lung tissue only tumor suppressor genes (CDKN1A/p21, CDKN1C/p57, RBL2/p130) and the cyclin D family were overexpressed, reflecting a normal phenotype." (PMID 25325012, 2014). "Compared to the staining intensities for RBL2 and HP1γ, the signal was always found weaker in MLS tumor tissues and RB1 staining was also weaker in MLS tissues compared to reference tumor tissues of other entities." (PMID 25093008, 2014). "In addition to these tumour suppressor genes, PRMT5 also reduces transcription of RB family tumour suppressor genes including RB1, RBL1 and RBL2 in transformed B‐cell lymphocytic leukaemia cell lines." (PMID 33462997, 2021). "Interestingly, some upregulated genes, such as Myb, Rbl2 and Cyclin-dependent kinase inhibitor 2A (CDKN2A; fold change: 2), code for proteins able to act as tumor suppressors." (PMID 27876093, 2016).
tumor (continued). "Thus, we inferred that the down-regulation of C1orf132 might release the miRNAs that targeted RBL2 and CCND3 and further promote the tumor progression, which warrant further in-depth experimental research." (PMID 28587642, 2017). "Some studies reported that RBL2 and CCND3 may behave as tumor suppressors in LUAD." (PMID 28587642, 2017). "We also identified six UPRs unique to CPA-treated B16F10 tumors vs. GL261(B6) tumors that promote tumor cell survival or tissue repair and may contribute to B16F10 tumor unresponsiveness: activated UPRs KDM5B, RBL2 and SPARC; and inhibited UPRs FOXM1, CD24 and CSF2)." (PMID 27515027, 2016). "Collectively, these results suggested that the expression of human RB family tumor suppressors does not abolish the self-renewal capacity of hESCs, while RBL2 could impact the expression of WNT and NOTCH developmental signaling pathways and Hox genes in differentiating cells." (PMID 37725511, 2023). "The paracrine regulation of tissue formation by RBL2 demonstrates that RBL2 is not simply regulating the cell cycle as a tumor suppressor in a cell-autonomous manner but could also have a function in regulating the extracellular niche of stem cells and progenitors." (PMID 37725511, 2023). "They showed that four tumor-specific mRNA (ALOX5, RBL2, VEGFA, TLK2) present in EVs (defined as present in tumor-derived-, urine- and plasma-EVs, but absent in tumor-adjacent tissue EVs) may be used as RCC biomarkers in the future." (PMID 35629194, 2022).